PGC (progastricsin)
Diseases named in the same sentence as PGC in open-access papers (continued):
Sharing a sentence is not in itself a finding about the gene and the disease.
atrophic gastritis (14 papers, 2003 to 2024). "Subsequently, the SNPs in pepsinogen C (PGC), just located in 6p21.1, was found to play an important role in altering susceptibility to atrophic gastritis (AG) and GC by our research group in 2014." (PMID 29221129, 2017). "The interaction effect on atrophic gastritis risk between PGC rs6912200 and PTPN11 rs12229892 (OR = 0.60) was greater than the main effect of a single polymorphism, PGC rs4711690 (OR = 0.78) that was identified in our previous study." (PMID 26158864, 2015). "Our research group previously found another interaction effect between PGC rs4711690 polymorphism and H. pylori infection in the development of atrophic gastritis." (PMID 25551587, 2014). "Pri-let-7a-1 rs10739971 polymorphism and PGC rs65458238 and rs9471643 polymorphisms had interaction effects for the risk of atrophic gastritis (Pinteraction = 0.012 and 0.039, respectively)." (PMID 24586594, 2014). "Because pri-let-7a-1 rs10739971 polymorphism demonstrated interaction effects with both PGC SNPs on atrophic gastritis risk, we further carried out interaction analysis of the three positive polymorphisms." (PMID 24586594, 2014). "The pair of pri-let-7a-1 rs10739971 polymorphism and PGC rs9471643 polymorphism had an OR of their interaction of 0.52 for atrophic gastritis risk." (PMID 24586594, 2014). "Examples of corpus-specific proteins that were decreased or lost in atrophic gastritis include multiple subunits of the parietal-cell specific H+/K+ ATPase, as well as the proteolytic enzyme gastricsin (derived from the precursor progastricsin, also known as pepsinogen II, encoded by the Pgc gene)." (PMID 38059647, 2024). "This study aimed to explore the interaction of the let-7e rs8111742, miR-365b rs121224, and miR-4795 rs1002765 single nucleotide polymorphisms (SNPs) with SNPs of the predicted target gene PGC and Helicobacter pylori status in GC and atrophic gastritis (AG) risk." (PMID 26988755, 2016). "Similarly, the pair of pri-let-7a-1 rs10739971 polymorphism and PGC rs6458238 polymorphism had an OR of their interaction of 2.77 for atrophic gastritis risk, which was larger than their individual single-locus effects of 0.74 and 1.23, respectively." (PMID 24586594, 2014). "Our previous studies in normal gastric mucosa, atrophic gastritis (precancerous disease group) and the gastric disease chain showed that PGC protein levels decrease gradually with disease progression." (PMID 28067243, 2017). "A three-way interaction between PGC rs4711690 CG/GG, PGC rs6912200 CT/TT, and PTPN11 rs12229892 GA/AA was significantly associated with atrophic gastritis risk (P value for interaction = 0.048, interaction index = 2.82)." (PMID 26158864, 2015). "PGC protein has a protective effect in the epithelium of the normal stomach, and its expression decreased in an atrophic gastritis group when compared with a normal group." (PMID 24586594, 2014). "The aim of this study was to validate these serum biomarkers, that is pepsinogen A (PGA), pepsinogen C (PGC), PGA/PGC ratio, and gastrin, as screening tests for precancerous lesions: atrophic chronic gastritis (ACG) or Helicobacter pylori-related corpus-predominant or multifocal atrophy." (PMID 12698190, 2003). "In the process from superficial gastritis to atrophic gastritis and finally to the formation of GC, the positive level of PGC continues to decline, which indicates that the in situ expression of PGC may have a negative correlation with the formation of GC." (PMID 34840985, 2021).
breast carcinoma (10 papers, 1993 to 2024). "PGC mRNA expression was positively linked to the relapse-free survival rate of the breast cancer patients (p < 0.05)." (PMID 37291517, 2023). "PGC mRNA expression was higher in invasive lobular carcinoma than in ductal carcinoma (p < 0.05), positively associated with ER and PR expression in breast cancer (p < 0.05), and negatively associated with the aggressiveness of PAM50 subtypes (p < 0.05)." (PMID 37291517, 2023). "In particular, lactalbumin alpha (LALBA) and progastricsin (PGC) were replicated with strong evidence of association with breast cancer risk." (PMID 32856720, 2021). "The results of this study show that PGC was closely related to androgen response pathway and estrogen response pathway, suggesting that PGC participates in hormone‐related pathways and plays a regulatory role in the occurrence and development of breast cancer." (PMID 33067881, 2020). "In addition, PGC expression was positively linked to the ER and PR expression of breast cancer and was lowest in TNBC, suggesting that PGC loss is closely linked to the tumorigenesis and histogenesis of TNBC." (PMID 37291517, 2023). "PGC expression levels were apparently up-regulated in hepatocellular carcinoma, prostate cancer, breast cancer, ovarian cancer, endometrial cancer, pancreatic cancer, kidney cancer, bladder cancer, eyelid basal cell carcinoma, squamous cell carcinoma and melanoma." (PMID 37291517, 2023). "Beside, PGC also have close relationship with ovarian cancer, breast cancers, and prostatic cancer." (PMID 33067881, 2020). "In sex-related tumours such as prostate cancer, breast cancer and ovary cancer, PGC upregulation is an indicator that hormones might play a vital role in regulating PGC expression." (PMID 28546787, 2017). "PGC expression levels were apparently promoted, especially in the tumour, for example, in prostate cancer, breast cancer, ovary cancer, endometrial cancer, pancreatic cancer, kidney cancer, bladder cancer, eyelid basal cell carcinoma, squamous cell carcinoma and melanoma, etc.." (PMID 28546787, 2017). "Incubating breast cancer cells with dihydrotestosterone, progesterone or the synthetic glucocorticoid dexamethasone for 48 h could induce 1.5-kbp PGC mRNA aggregation and PGC protein expression." (PMID 28546787, 2017). "Therefore, we believe that the PGC promoter might possibly be specific for the breast lobule, and any genetic alteration in the breast lobule might result in breast cancer." (PMID 37247123, 2023). "The PGC gene FUS1 (also known as FUS) has been reported as a tumor suppressor gene in lung and breast cancer and a pro-oncogene in leukemia." (PMID 18636107, 2008).
gastric diseases (8 papers, 2013 to 2024). "However, Pinto-Correia reported that PGC homozygous allele 1 was related to the up-regulation of PGC expression to serve as a protective factor in the development of gastric disease." (PMID 28546787, 2017). "APOA1BP, PGC, HPX, and DDT were discovered to be connected to the risk of gastric disease progression and to be able to forecast the progression of gastric disease in a prospective study on proteomic analysis, GPL, and early gastric cancer." (PMID 37719006, 2023). "In the present study, we determined the expression of 6 biomarkers in different gastric diseases, including differentiation (PGC, MG7‐Ag), migration (MMP9 and NM23), proliferation (Ki‐67), and epithelial mesenchymal transition‐related protein (E‐Cadherin)." (PMID 29963765, 2018). "To explore the correlation between PGC and other positive tumor markers in different gastric diseases, we observed the expression of PGC, MG7‐Ag, MMP9, NM23, Ki‐67, and E‐cadherin by immunohistochemistry, quantitative RT‐PCR, and immunoblot analysis." (PMID 29963765, 2018). "Serum PGC concentration increased gradually with the exacerbation of gastric disease from SG → SG with intestinal metaplasia → AG → dysplasia → GC." (PMID 28546787, 2017). "Very interestingly, the lncRNA genes where our studied SNPs located are just adjacent to PGC, a specific marker related to gastric diseases quite intimately." (PMID 29221129, 2017). "As physiologically functional gastric proteins and “ectopic” expressed protein, the association of PGC, MUC1 and MUC2 solely and gastric diseases had been reported in the past." (PMID 23937908, 2013). "As we know, PGC, MUC1, MUC2, the three proteins had solely important diagnostic role for the gastric disease." (PMID 23937908, 2013). "The expression of PGC protein decreased gradually with gastric disease progression." (PMID 28067243, 2017). "Serum PGC is related with cancers of other organs beyond initial gastric diseases." (PMID 28546787, 2017). "Phenotypes of PGC, MUC1 and MUC2 co-expression in dynamic gastric diseases are variable." (PMID 23937908, 2013). "We aimed to investigate the co-expression of PGC, MUC1 and MUC2 which might also give a clue for the understanding of the progression of gastric diseases." (PMID 23937908, 2013).
diabetes (4 papers, 2015 to 2024). "Our results suggest that CNP/NPR-A, B/pGC/cGMP/PDE3/cAMP signal pathway may be associated with the diabetes-induced gastric motility disorder." (PMID 25883642, 2015). "Interestingly, several DEGs identified in this study had been reported to be associated with the occurrence and progression of diabetes, including SERPINF1, PID1, IL1R1 and PGC." (PMID 39845878, 2024). "However, diabetes induces upregulation of NPRs/pGC/cGMP signal pathway and the subsequent increase of cGMP is responsible for the downregulation of PDE3 expression, which finally inhibits cAMP hydrolysis and increases intracellular cAMP in gastrointestinal smooth muscle." (PMID 25883642, 2015). "Therefore, we suppose that diabetes-induced upregulation of NPRs in gastric smooth muscle potentiates CNP/NPR-A, B/pGC/cGMP-PDE3-cAMP signal pathway." (PMID 25883642, 2015).
gastric adenocarcinoma (4 papers, 2020 to 2024). "The results showed that PGC gene mutations frequently occurred in uterine corpus endometrial carcinoma and stomach adenocarcinoma." (PMID 33067881, 2020). "Genetic variation analysis showed that PGC gene often mutated in uterine corpus endometrial carcinoma and stomach adenocarcinoma had extensive copy number amplification in various tumor types." (PMID 33067881, 2020). "Here, we found no gastric carcinogenesis in transgenic mice expressing T antigen in pit and parietal cells, while we observed gastric adenocarcinomas in K19- or PGC-cre/T antigen mice, and gastric adenoma in Pdx1-cre/T antigen mice." (PMID 37247123, 2023). "In addition, it is of particular note that PGC was involved in 33 signal pathways, mainly in three cancers including stomach adenocarcinoma, esophageal carcinoma and lung squamous cell carcinoma." (PMID 33067881, 2020). "In cholangiocarcinoma, esophageal cancer, and kidney renal papillary cell carcinoma, PGC expression was upregulated with the increase of copy number, but in stomach adenocarcinoma, both increase and deletion of PGC copy number could lead to the up‐regulation of PGC expression." (PMID 33067881, 2020). "By retrieving published literature, we also found supporting evidence that the expression of PGC in situ in gastric mucosa has a good correlation with the occurrence and development of stomach adenocarcinoma, and it is an ideal "negative marker" for stomach adenocarcinoma." (PMID 33067881, 2020). "PGC expression was upregulated with the increase of copy number in cholangiocarcinoma, esophageal carcinoma, and kidney renal papillary cell carcinoma, while in stomach adenocarcinoma, PGC was upregulated regardless of whether the copy number was increased or decreased." (PMID 33067881, 2020).
adenoma (3 papers, 2004 to 2023). A neoplasm arising from the epithelium. "MNU-treated WT mice exhibited globoid dysplasia and well- and poorly differentiated carcinoma, whereas MNU-treated PGC KO mice showed adenoma, regenerative and globoid dysplasia, and well- and moderately differentiated adenocarcinoma." (PMID 37291517, 2023).
colon cancer (3 papers, 2001 to 2011). "In a multivariate analysis, PGC expression behaved as an independent prognostic factor compared to other clinical variables in the breast and colon cancer cohorts, and was associated with tumor stage in ovarian, lung and glioma cancer patients." (PMID 18636107, 2008).
esophageal cancer (3 papers, 2020 to 2024). A primary or metastatic malignant neoplasm involving the esophagus. "This study comprehensively investigates PGC expression across cancers, particularly in esophageal cancer (ESCA), to clarify its role in BE progression to EAC." (PMID 39767224, 2024). "The results of this study further confirmed that PGC is involved in the regulation of esophageal carcinoma." (PMID 33067881, 2020). "We performed gene set enrichment and SODEGIR analyses to identify enrichment in TREM1, PGC, INHBA, and AGR, all of which are involved in cancer-related pathways and associated with patient prognosis in esophageal carcinomas and premalignant Barrett’s epithelium." (PMID 39123475, 2024).
heart failure (3 papers, 2017 to 2024). Inability of the heart to pump blood at an adequate rate to meet tissue metabolic requirements. "Thus, disturbances in the mitochondrial electron transport chain via DOX-Top2β-PGC may lead to the one-, two-, and three-electron reduction of oxygen and trigger oxidative stress and the snowball effect in mitochondria, leading to heart failure." (PMID 39769331, 2024).
lung carcinoma (3 papers, 2011 to 2022). "In this study, we first systematically analyzed the expression of eight AT II-associated genes (AQP4, SFTPB, SFTPC, SFTPD, CLDN18, FOXA2, NKX2-1, and PGC) in lung cancer." (PMID 36203529, 2022). "In this study, we comprehensively analyzed the gene expression, prognosis value, genetic alteration, and immune cell infiltration of eight AT II-associated genes (AQP4, SFTPB, SFTPC, SFTPD, CLDN18, FOXA2, NKX2-1, and PGC) in Nonsmall Cell Lung Cancer (NSCLC)." (PMID 36203529, 2022). "At the protein expression level, only a small amount of PGC expression was detected in lung cancer, prostate cancer, and thyroid carcinoma, but no PGA expression was detected." (PMID 33067881, 2020).
ovarian cancer (3 papers, 2016 to 2020). A primary or metastatic malignant neoplasm involving the ovary. "The PGC gene has a general role in suppressing tumordevelopment and several studies reported that low expression of PGC protein was closely related to poor differentiation and unfavorable survival in patients with breast, prostate, gastric and ovarian cancers." (PMID 27081700, 2016).
atrophic chronic gastritis (2 papers, 2003 to 2014). "Therefore, we considered the subjects with endoscopically- and histopathologically-confirmed normal stomach and slight superficial gastritis as eligible samples for PGC expression experiment in situ." (PMID 25551587, 2014).
breast tumours (2 papers, 1993 to 2008). "PGC encodes for pepsinogen C, a proteolytic enzyme involved in digestion, which is expressed in breast tumours." (PMID 18507837, 2008).
glioblastoma (2 papers, 2024). The most malignant astrocytic tumor (WHO grade IV). "Consequently, the modulation of PGC metabolism is highlighted as a potential target for intervention in glioblastoma treatment." (PMID 39135106, 2024).
glioma (2 papers, 2008 to 2017). A benign or malignant brain and spinal cord tumor that arises from glial cells (astrocytes, oligodendrocytes, ependymal cells). "Pharmacologically manipulating endogenous cGMP generation in glioma cells through either stimulating pGC by ANP/BNP or blocking PDE by 3-isobutyl-1-methylxanthine/zaprinast caused significant inhibition of proliferation and colony formation of glioma cells." (PMID 29333177, 2017). "Second, the reduced variation of the PGC genes was consistently observed in multiple independent sets from diverse tissues (e.g. gliomas, lung, breast), including a data set (NCC) that combined tissues from two different sources (gastric and NPC tumors)." (PMID 18636107, 2008).
hepatocellular carcinoma (2 papers, 2020 to 2023). A malignant tumor that arises from hepatocytes. "Previous studies have shown that PGC expression and tumor size are independent prognostic factors for overall survival and disease‐free survival in hepatocellular carcinoma." (PMID 33067881, 2020).
Hyperinsulinemia (2 papers, 2018 to 2021). An increased concentration of insulin in the blood. "Metformin and hyperinsulinemia changed the expression of extracellular proteins (e.g. metformin: CTSL, EGFR, IL5, KLK3; insulin: IL4, IL15, PGC, SORL1)." (PMID 33690729, 2021).
melanoma (2 papers, 2020 to 2023). A malignant, usually aggressive tumor composed of atypical, neoplastic melanocytes. "Concerning the molecular player of the pGC-cGMP signaling in highly metastatic melanoma cells, we reported a strong reduction in the expression of both GC-A and GC-B under simulated microgravity conditions in comparison to 1 g controls." (PMID 32046325, 2020). "Concerning the role of pGC in melanoma, it has been shown that a large increase of CNP as a ligand of GC-B, which is released by the tumor vasculature particularly under inflammatory conditions, enhances the activity of PKGI in melanoma cells by increasing the intracellular cGMP concentration." (PMID 32046325, 2020).
Obesity (2 papers, 2016 to 2022). Accumulation of substantial excess body fat. "We only found five genes shared between both groups (MUCL3, PGC, TCN1, TFF2, BPIFB1) that were upregulated in MO-low-IR but downregulated in MO-high-IR when compared with women without obesity." (PMID 35625760, 2022).
seminoma (2 papers, 2015 to 2016). A radiosensitive malignant germ cell tumor found in the testis (especially undescended), and extragonadal sites (anterior mediastinum and pineal gland). "In seminoma-like TCam-2-ΔSOX2 cells SOX17 expression is maintained and presumably partners with OCT3/4 to bind the canonical motif, triggering expression of PGC-, GCNIS- and seminoma-related genes, allowing keeping up the seminoma-like cell fate." (PMID 27283990, 2016). "However, with downregulation of PGC- (PRDM1, TFAP2C, cKIT) and pluripotency (NANOG, OCT3/4, LIN28) marker genes, persisting SOX17 expression together with activation of the Hippo pathway resulted in differentiation into a mixed non-seminoma with predominant choriocarcinoma-like components." (PMID 26226633, 2015).
acne (1 paper, 2025). An inflammatory process of the sebaceous glands which is characterized by comedones, nodules, papules and/or pustules on the skin. "GO terms and KEGG pathway enrichment analyses of the PPI network indicated that PGC may influence apoptosis, cell cycle, inflammation, and adipocyte‐related signaling pathways, which appear to play regulatory roles in acne, atopic dermatitis, eczema, and skin barrier impairment." (PMID 40762221, 2025).
Ataxia (1 paper, 2014). Ataxia refers to impaired coordination of voluntary muscle movement. "Taken together, these data demonstrate that the motor phenotype of PGC-1α−/− mice includes ataxia characterized by altered gait kinematics, including increased stance duration, increased paw placement, and stepping mistakes." (PMID 25610371, 2014).
bipolar disorder (1 paper, 2022). A disorder of the brain that causes unusual shifts in mood, energy, activity levels and the ability to carry out day-to-day tasks. "Based on the previous investigation of risk genes for bipolar disorder, we hypothesized that the PGC risk genes will also show a greater interaction with each other than would be observed in randomly selected sets of genes." (PMID 35741803, 2022).
colorectal adenocarcinoma (1 paper, 2023). The most common type of colorectal carcinoma. "Here, we first observed spontaneous colorectal adenocarcinomas in villin-cre/T antigen and PGC-cre/T antigen mice, indicating the potential oncogenic role of JCPyV T antigen in colorectal carcinogenesis." (PMID 37247123, 2023).
cyst (1 paper, 2022). A sac-like closed membranous structure that may be empty or contain fluid or amorphous material. "A recent biomarker discovery effort of cyst fluids identified pepsinogen C (PGC) in mucinous pancreatic cyst." (PMID 35741154, 2022).